IL23R (interleukin 23 receptor)
Diseases named in the same sentence as IL23R in open-access papers (continued):
Sharing a sentence is not in itself a finding about the gene and the disease.
cancer (continued). "As a key component of immune regulation, IL-23R significantly influences innate immunity and inflammatory signaling, influencing the development, progression, and therapeutic response of many cancers including HCC." (PMID 39921803, 2025). "It has been shown that cancer-free adults with the rs10889677 AA genotype exhibited a higher expression of IL-23R in peripheral blood mononuclear cells relative to those with the AC/CC genotype." (PMID 38810984, 2024). "The role of IL-23R in cancer is complex, exhibiting both pro-tumorigenic and anti-tumorigenic effects depending on the circumstances." (PMID 39796684, 2024). "In conclusion, the evidence suggests that IL-23R plays a crucial role in the interaction between the immune system and different types of cancer." (PMID 39796684, 2024). "The discovery of IL23R variant rs10889677 as a possible mutation may help to give an insight on how the cytokine-induced PI3K pathway links inflammation with a higher risk of developing cancer, opening the door to improved care for CAC patients in the near future." (PMID 36232773, 2022). "Since IL-23 is needed to sustain Th17 cells, the role of Th17 cells in premalignant lesion development and progression to cancer was determined in 4NQO-treated wildtype mice and IL-23R KO mice." (PMID 29664967, 2018). "Production of IL-4 by spleen cells of IL-23R KO mice increased slightly as lesions advanced to cancer, at which point similar levels were produced by spleen cells of the IL-23R KO and wildtype mice." (PMID 29664967, 2018). "IL-10 production by spleen cells of IL-23R KO mice remained at a relatively constant level even as lesions advanced to cancer, although at this latter time point IL-10 production by spleen cell of wildtype mice increased." (PMID 29664967, 2018). "Our study suggestsTh17 cells are likely to be protective in mice with premalignant oral lesions as lesions advanced toward cancer more readily in the IL-23R KO mice which had a reduced Th17 phenotype." (PMID 29664967, 2018). "Clinically, early progression of premalignant oral lesions to cancer was enhanced in IL-23R KO mice compared to progression in wildtype mice." (PMID 29664967, 2018). "In the wildtype mice, levels of CD4+ cells expressing IFN-γ declined at the later stages during the onset of cancer, while in the IL-23R KO mice, the levels of these cells remained constant throughout the course of lesion development and progression." (PMID 29664967, 2018). "IL-23R was exclusively expressed in infiltrating inflammatory cells in both cancer and normal tissues, but the expression level and ratio were much higher in cancer tissues." (PMID 25349535, 2014). "As a key element in the T-helper 17 (Th17) cell-mediated inflammatory process, interleukin-23 receptor (IL-23R) plays a crucial role in the pathogenesis of cancer." (PMID 24586528, 2014). "Our results highlight a previously unrecognized role of IL-23R that can be potentially explored as a therapeutic agent against human cancers." (PMID 24351840, 2013). "Here, this unexpected role of IL-23R signaling in stabilizing Treg suppressive functions sets the sound base for the therapeutic targeting of Treg cells through IL-23 or IL-23R blockade to expand the armamentarium of cancer immunotherapy." (PMID 38356059, 2024). "IL-23R plays a significant role in the pathogenesis of cancer." (PMID 39796684, 2024). "Furthermore, numerous IL-23R SNPs have been identified in a multitude of cancers and inflammatory disease-related conditions, with direct or indirect consequences for the amino acid sequence." (PMID 39796684, 2024). "Likewise, reverse correlation in VGF expression and IL23R expression was also noted in nearly all malignant tumor types (11/12) in the TCGA database, including those carcinomas in breast and prostate, NSCLC, and CRC." (PMID 38528565, 2024).
cancer (continued). "Accordingly, further investigation of IL-23R’s role in tumors and in cancer development seems warranted and may lead to the design of new drug profiles and innovative strategies that can alter IL-23/IL-23R signaling." (PMID 39796684, 2024). "Our data support that targeting the IL-23/IL-23R axis in cancer may represent a means of eliciting antitumor immunity." (PMID 38356059, 2024). "Notably, our analysis of TCGA data suggests that elevated IL23R expression is specific to CRC compared to other cancer types." (PMID 38375204, 2023). "Moreover, we observed a marked increase in the expression of IL-23R and IL-17A in both cancer cell lines when co-cultured with educated DCs as compared to uneducated DCs." (PMID 34680308, 2021). "Moreover, we observed a marked increase in the expression of IL-23R and IL-17A in both cancer cell lines when co-cultured with educated macrophages as compared to uneducated macrophages." (PMID 34680308, 2021). "In addition, the expression of Oct-4A, a marker of self-renewal, undifferentiated stem cells or poor prognosis for patient with cancers, co-localized with the IL-23R+ ESCCs." (PMID 30483821, 2019). "Interestingly, we also confirmed expression of IL-23R in CSLCs derived from cancer cell lines and primary cancer specimen." (PMID 27738346, 2016). "For regulatory T cells (Tregs), the IL-23R signaling pathway might also promote the immunosuppressive function of Tregs facilitating evasion of the immune system by cancer cells." (PMID 24278297, 2013). "IL-23R gene might have the great potential to be developed as a therapeutic target against human cancers." (PMID 24351840, 2013). "Our data reveals that RAS/MAPK signaling pathway that is connected with STAT3 signaling pathway might be the central mitogenic pathway negatively regulated by IL-23R in transformed or cancer derived mammalian cells." (PMID 24351840, 2013). "IL23R-expressing Treg cells could be identified across a wide variety of human cancer entities." (PMID 38356059, 2024). "Given its dual functionality, the IL-23/IL-23R axis is being investigated as a potential target for immunotherapy in cancer, as well as a modulator that may be combined with other treatments to enhance anti-cancer immunity." (PMID 39796684, 2024). "However, no mutations were identified in the cancer hotspot locations of IL23R, IL12Rß1, IL12Rß2, OSMR, TYK2, and JAK2 across all mutant distributions." (PMID 36232773, 2022). "Hence, introducing IL23R as the next cancer small-molecule inhibitor may be advantageous for future therapies." (PMID 36232773, 2022). "Because of the differences in cytokine production by spleen cells of lesion-bearing wildtype versus IL-23R KO mice, studies were conducted to determine the impact of blocking IL-23 signaling on the splenic T-cell composition during lesion development and progression to cancer." (PMID 29664967, 2018). "therefore, the association between IL-23R rs10889677A>C polymorphism and the risk for ESCC in Chinese population remains unclear, and case-control studies with large sample sizes and different cancer types are needed." (PMID 24586528, 2014). "Treg cells represented the main IL23R-expressing cancer T cell cluster, accounting for over 50% of the IL23R+CD4+ T cells and 29% of total IL23R+ pan-cancer T cells." (PMID 38356059, 2024). "After looking through papers, only 4 genes of these prognostic markers have been verified to be relavant with according cancers, including CCL4 in COAD, CACNA2D3 and SMO in ESCA, and IL23R in LUAD." (PMID 31888612, 2019). "However, once the lesions had advanced, Treg and IL-10 levels increased in the wildtype but not the IL-23R KO mice, suggesting that at the later stages, Th17 cells could be contributing to the cancer–associated immune suppression." (PMID 29664967, 2018).
cancer (continued). "However, surprisingly, based on a high expression of IL-23 and IL-23R in CD133+ ovarian CSLCs derived from cancer cell lines and primary cancer tissue, we found autocrine IL-23 could promote the self-renewal capacity and tumorigenic potential of CD133+ ovarian CSLCs both in vitro and in vivo." (PMID 27738346, 2016). "Interleukin 23 receptor (IL-23R) is a key player in the pro-inflammatory signal transduction pathway of the IL-23/IL-17 axis (IL-23→IL-23R→STAT3→Th17→IL-17/IL-17F) and is recognized for its crucial role in inflammatory diseases and cancers." (PMID 38810984, 2024). "As the initial element, the baseline expression level of IL-23R was not significantly different between cancer cell lines and remained relatively constant, albeit weak in Het-1A cells before and after treatment with IL-23." (PMID 30483821, 2019). "In contrast, as lesions progressed to cancer, the pro-inflammatory phenotype subsided and was replaced with the inhibitory mediator IL-10 and with Treg cells in wildtype mice, although not in IL-23R KO mice." (PMID 29664967, 2018). "Furthermore, the IL-23R KO mice lacked the increases in Treg and IL-10 levels that were seen in wildtype mice as lesions advanced to cancer." (PMID 29664967, 2018).
infection (24 papers, 2011 to 2024). The state of being infected such as from the introduction of a foreign agent such as serum, vaccine, antigenic substance or organism. "Gene expression analysis demonstrated a strong upregulation of IL23A (encodes p19) by infection, whereas IL23R, Epstein–Barr virus-induced gene 3 (EBI3), IL6ST, IL12A, and IL27RA were found to be expressed, but not regulated, or to a lesser extent." (PMID 24069393, 2013). "The nominally significant association between IL23R p.V324 M and body weight under infection indicates that this SNP may be worthy of further investigation in additional, larger sheep populations to test its association with nematode resistance." (PMID 28807314, 2017). "The Vδ1 IL-23R+ expression was different in the three groups (p = 0.001), with fewer Vδ1 T cells expressing IL-23R in the infection group than in the control group (p = 0.001)." (PMID 32560376, 2020). "For another Th17-associated pathway, IL23R interacts with IL23 to regulate the activity of immune cells and plays an important role in the inflammatory response against infection by bacteria and viruses." (PMID 31615448, 2019). "Two days after infection, the cells were fixed and analyzed by immunofluorescence with antibodies against IL-23R." (PMID 28593439, 2017). "Our finding supports this observation, as we observed down-regulation of IL23/IL23R after infection." (PMID 27661612, 2016). "However, we observed that Th17-related genes (IL-17F, IL-17RD, IL-23, and IL23R) were significantly downregulated, which is similar to previous findings on F. hepatica-induced infection in ovine peripheral blood mononuclear cells." (PMID 35320269, 2022). "As expression of the IL-23R is a hallmark of Th17 phenotype, our data suggest that immunity to infection is predominantly based upon a Th17 response, rather than a Th1 response." (PMID 31658288, 2019). "This downregulation of IL23R in our study may indicate an attenuation of pathogenicity of Th17 cells during infection." (PMID 27661612, 2016). "In addition, IL23R exhibits a copy number variation (CNV), which could contribute to individual’s diversity in host response during infection and inflammation, and is possibly associated with TB." (PMID 26626589, 2015). "Our results indicate that the expression of IL6, IL12B, IL1R2, IL23R, IL12RB1 and IL12RB2 increased after DTMUV infection." (PMID 35585616, 2022). "While IL1R2, IL23R, IL1R1, IL-10, and CCL24 were highly upregulated upon infection of THP-1 macrophages, their expression was barely affected upon infection of primary macrophages." (PMID 34276658, 2021). "We found an increased expression of IL7R, IL23R (both strains) and IL21R (Eystrup only) by cDC1 and cDC2 subsets, while pDC downregulated IL7R (Eystrup) and upregulated IL21R following infection (both CSFV strains)." (PMID 32733474, 2020). "As only 10% of CD4+RORγt+ T cells from patients with infection expressed IL-23R, this suggests that activation of a relatively small proportion of the potential pool of CD4+ Th17 cells is required to control infection." (PMID 31658288, 2019). "HEK293 cells were infected with Ad5–IL-23R, Ad5–FLAG–IL-23R, Ad5–sIL-23R, and Ad5–FLAG–sIL-23R with a multiplicity of infection of 2 in order to analyze the cellular distribution of IL-23R and sIL-23R." (PMID 28593439, 2017). "Following infection with BCG, intracellular IFN-γ induction was mildly impaired in CD4+ T cells and more severely in MAIT and Vδ2+ γδ T cells of IL-23R-deficient patients, and this impairment was not rescued by exogenous IL-12." (PMID 36763636, 2023). "Qiu and colleagues (2012) found that AHR-deficient ILCs lack the IL-23 receptor (IL-23R) and that AHR KO mice express IL-22 at reduced levels and, unlike wild-type mice, succumb to infection with C. rodentium." (PMID 32784381, 2020). "The expression of IL-23R on kidney NK cells was upregulated in control but not CD11cΔSyk mice following infection." (PMID 25033445, 2014).
infection (continued). "On the other hand, IL23R was found to be downregulated in MKN-28 cells after 48h of infection with P1 and its two isogenic mutants (P<.05), but not with BCM-300 strain." (PMID 24069393, 2013).
immune diseases (9 papers, 2011 to 2024). "It is considered to be a T cell-dependent immune disease whose pathogenesis is influenced by cytokines, such as IL-10, IL-17A, IL-17RA, IL-23A and IL-23R." (PMID 34945130, 2021). "The most common IL-23R SNP related to immune diseases are rs7517847, rs11209032, and rs1343151, although rs17375018 was not shown to be associated with other diseases, it was found to be associated with Behcet’s in our laboratory of Ophthalmology; therefore, these 4 were analyzed in our study." (PMID 23696856, 2013).
inflammation (6 papers, 2010 to 2025). Aberrant reaction of the microcirculation characterized by movement of fluid and leukocytes from the blood into extravascular tissues. "IL23R (Interleukin 23 receptor) also plays an important role in the development of chronic intestinal inflammation, among other things by regulating the immune response associated with Th17 lymphocyte activity." (PMID 41300823, 2025). "At the experimental endpoint no changes in weight loss or colonic inflammation were observed by histology indicating that IL-23R signaling in colonic Treg cells is not required for chronic intestinal inflammation induced by chronic DSS." (PMID 38375204, 2023).
infectious disease (5 papers, 2022 to 2025). A disorder directly resulting from the presence and activity of a microbial, viral, or parasitic agent in humans. "We investigated the role of human IL-23 in host defense further, by searching for new patients with AR IL-23R deficiency in a cohort of >15,000 patients with diverse infectious diseases." (PMID 36763636, 2023). "Several studies have shown that genetic variations in Th17 pathway genes (including IF-17A, IF-17F, IL-21, and IL-23R) are associated with infectious disease susceptibility and clinical manifestations." (PMID 36483566, 2022). "We searched for non-synonymous, essential splice site, or copy number variants of IL23R in a cohort of >15,000 patients with highly diverse infectious diseases, including 1,618 patients with MSMD, 1,454 with TB, and 730 with CMC." (PMID 36763636, 2023).
bacterial infection (2 papers, 2010 to 2020). "Furthermore, since IL-23R signalling promotes the expansion and maintenance of γδ T cells in response to intracellular bacterial infection, the ability of pneumolysin to promote both IL-1 and IL-23 production is likely to contribute strongly to these γδ T cell responses." (PMID 21085613, 2010).
adenocarcinoma (1 paper, 2013). A common cancer characterized by the presence of malignant glandular cells. "Apilimod may however be a beneficial treatment option for NSCLC patients that express a functional IL-23R, given that it results in significant decreases in proliferation in the A549 adenocarcinoma cell line which expresses higher levels of the IL-23R than the SK-MES-1 cell line." (PMID 23802098, 2013).
digestive system cancer (1 paper, 2012). A primary or metastatic malignant neoplasm involving any part of the digestive system. "IL23R single nucleotide polymorphisms (SNPs) have been shown to be associated with digestive system cancers." (PMID 23239971, 2012).
hematologic malignancies (1 paper, 2013). "The interleukin-23 (IL-23) and its receptor (IL-23R) mediate the direct antitumor activities in human hematologic malignancies including pediatric acute leukemia." (PMID 23393581, 2013).
IL23R also shares sentences with these, for which no sentence is quoted: spondylitis (4 papers); dermatitis (3); melanoma (3); acne (2); acute myeloid leukaemia (2); chronic periodontitis (2); Graves ophthalmopathy (2); Hypertension (2); juvenile idiopathic arthritis (2); liver cancer (2); nephritis (2); prostate carcinoma (2); systemic sclerosis (2); age-related macular degeneration (1); Alzheimer disease (1); anaplastic large cell lymphoma (1); atopic asthma (1); autoimmune polyendocrine syndrome type 1 (1); autoimmune thyroid disease (1); autoimmune uveitis (1); bacteremia (1); basal cell carcinoma (1); Blau syndrome (1); candidiasis (1); cardiovascular diseases (1); cerebral palsy (1); chronic rhinosinusitis (1); co-infection (1); disseminated candidiasis (1); encephalitis (1).
A further 44 diseases each share a sentence with IL23R in 1 paper.